NUMB (NUMB endocytic adaptor protein)
Diseases named in the same sentence as NUMB in open-access papers (continued):
Sharing a sentence is not in itself a finding about the gene and the disease.
tumor (continued). "However, many of the genes correlating with NUMBL showed an opposite behavior with NUMB in the other two analyzed pathways, WNT and Hedgehog, independently of the type of tumor." (PMID 29507685, 2018). "However, our analysis showed that NUMB and NUMBL exhibited almost independent correlations when we considered the four tumor types." (PMID 29507685, 2018). "Additionally, there was no mechanistic investigation, leaving questions about NUMB's precise involvement in tumor progression unanswered." (PMID 40296944, 2025). "NUMB was present in the network of GBM39, but there was no information about the invasiveness of this tumor line." (PMID 27354287, 2016).
cancer (65 papers, 2010 to 2025). A tumor composed of atypical neoplastic, often pleomorphic cells that invade other tissues. "SRSF3, together with hnRNP family splicing factor TDP43, also regulates cancer-associated NUMB exon 9 splicing." (PMID 39863103, 2025). "The underlying mechanism for NUMB Ex9in isoform effects in cancer cells is in part likely due to alterations in endocytic regulation of multiple membrane receptors." (PMID 39863103, 2025). "Phenotypically, in both RAB4A high/NUMB low and RAB4A low/NUMB high cancer cells, NUMB suppresses the long-term sphere formation—a hallmark of cancer stemness." (PMID 39463384, 2024). "In KEGG analysis, apart from multiple kinds of cancer, a number of signaling pathways, including Hippo, Neurotrophin, Thyroid hormone, and FoxO pathways, were associated with the functions of NUMB mutations." (PMID 37657045, 2023). "Our findings demonstrate a critical role of the SPTAN1/NUMB axis in cell density sensing, shedding light on the essential role of NUMB isoform splicing in the loss of cell contact inhibition and the initiation of cancer." (PMID 37843276, 2023). "The analysis of The Cancer Genome Atlas dataset revealed that low NUMB expression was associated with poor overall survival." (PMID 34883044, 2022). "Not surprisingly, considering its critical role in many cellular processes, subversion of NUMB has been linked to highly relevant human pathologies, including neurodegeneration and cancer." (PMID 25767773, 2015). "Together these studies point to a common mechanism that underlies the cancer-associated functions of Ex9in isoforms and suggest that NUMB isoform expression may bias endocytic trafficking and signaling of multiple cell surface receptors and adhesion molecules." (PMID 39863103, 2025). "In addition, NUMB deficiency results in differentiation failure of precursor cells, leading to numerous diseases, including developmental defects and cancer." (PMID 37843276, 2023). "In both HCC and ESCC, the expression of p72/p71 NUMB isoforms has been associated with increased early recurrence and lower overall survival after surgery due to increased proliferation, migration, and invasion in cancer cells." (PMID 36672267, 2023). "We next wanted to investigate whether NUMB isoforms were distinctly implicated in cancer metastasis using a xenograft assay in nude mice." (PMID 35457181, 2022). "In addition, the interaction of MSI/NUMB/Notch is considered to be associated with many malignant neoplasms in humans." (PMID 34073088, 2021). "Although the mechanisms underlying NUMB involvement in cancer are largely unknown, accumulating evidence suggests a critical role of NUMB in the EMT program." (PMID 27506933, 2016). "A similar role has also been demonstrated in human malignancy, including breast cancer, where loss of NUMB correlates with a less differentiated phenotype, expression of cancer stem cell traits and poor prognosis, salivary gland tumors, and non-small cell lung carcinomas (NSCLCs)." (PMID 25767773, 2015). "However, the underlying mechanism by which NUMB regulates EMT in cancer cells remains largely unknown." (PMID 27506933, 2016). "Inhibition of CRL7FBXW8 in NUMB‐LOF BC cells restores NUMB levels, and decreases the number of cancer stem cells and tumorigenic ability in vivo." (PMID 40411418, 2025). "Several of the splicing factors demonstrated to regulate NUMB isoform expression during development are themselves misregulated in cancer." (PMID 39863103, 2025). "The in vitro study of the signaling chain whereby RAB4A impacts cancer cell stemness has demonstrated that NUMB, NOTCH1, RAC1, and SOX2 are essential in mediating the regulatory effects of RAB4A on CSCs in multiple cancer cell lines of diverse tissue origins." (PMID 39463384, 2024).
cancer (continued). "The findings confirmed that RAB4A positively controls levels of NOTCH1 and SOX2, and negatively of NUMB, in these cancer cells." (PMID 39463384, 2024). "This miRNA also plays a role in oral carcinogenesis, promoting cancer cell proliferation and migration by targeting NUMB, IRAK and TRAF6." (PMID 36672267, 2023). "Although the roles of NUMB/NUMBL in the tumorigenesis and prognosis of several cancers have been partially confirmed, further systematical analysis, especially pan-cancer analysis, of NUMB/NUMBL has yet to be elucidated." (PMID 37657045, 2023). "Inversely, bioinformatic analysis also indicated significantly increased expression of NUMB in a few types of cancer, including CHOL, ESCA, HNSC, LAML, LIHC, PAAD, and STAD." (PMID 37657045, 2023). "In short, the observations above illustrated that relative mRNA expressions of NUMB/NUMBL were significantly related to patients individual cancer pathological stages." (PMID 37657045, 2023). "NUMB has been proposed to be involved in the regulation of multiple cellular pathways commonly altered in cancer, such as Wnt, Notch, or Hedgehog, due to its interactions with a wide variety of proteins." (PMID 36672267, 2023). "Recently, differential expression of NUMB has been proposed as a prognostic factor in various types of cancer." (PMID 36672267, 2023). "Together, our data demonstrated that the Notch1-SMAD3 interaction was important for NUMB isoforms-mediated cancer cell migration." (PMID 35457181, 2022). "Taken together, our data demonstrate that NUMB isoforms control cancer cell EMT and migration through the distinct regulation of Notch1-SMAD3 crosstalk." (PMID 35457181, 2022). "This longer NUMB isoform (Numb-L) was found to promote proliferation, whereas the shorter isoform (Numb-S) promotes differentiation of cancer cells." (PMID 36304260, 2022). "NUMB has been suggested to suppress tumors in several cancers, where NUMB expression is frequently downregulated in malignant cells." (PMID 34883044, 2022). "The association of NUMB isoforms and Notch1-SMAD3 complex with clinical outcomes in human cancers should be further addressed in future studies." (PMID 35457181, 2022). "Depletion of NUMB can lead to the increased expression of NOTCH target genes, which are implicated as therapeutic targets in the invasion of cancer cells." (PMID 34883044, 2022). "It remains to be characterized how the NUMB isoforms regulate cancer cell migration and cancer metastasis." (PMID 35457181, 2022). "Among the identified AS targets, specific CD44 and NUMB isoforms were shown to play specific and unexpected roles in stemness and cancer." (PMID 36346211, 2022). "As the suppressor role of NUMB is definitive, endogenous NUMB induction using the CRISPR/dCas-SAM system being tested in this study would be a potential option for cancer therapy." (PMID 34769160, 2021). "Bench study showed that, TUSC7 sponged to miR-146 and then released NUMB to control Notch signaling, the latter of which was critical for maintaining cancer stem cells (CSCs) pool." (PMID 34656164, 2021). "In our previous study, we found that KRT19 was obligatory for cancer and cancer stem cell progression because of its selective regulation of the NUMB-dependent Notch signaling pathway." (PMID 30650643, 2019). "The ability to normalize MSI-2/NUMB signaling by inducing differentiation of cancer SCs suggests a novel therapeutic approach for CRC treatment." (PMID 32984754, 2018). "This process has also recently been described for NUMB, showing that an altered isoform expression is common in cancer cells." (PMID 29507685, 2018). "The regulatory network analysis showed the association of some important hub proteins like GSK3B, NUMB, PEG3, ITGA2 and DLG2 with cancer-associated pathways." (PMID 28587194, 2017). "The latest research showed that MAP17 (a Cargo Protein) induces an increase in stem cell factors and cancer-initiating–like cells by sequestering NUMB to activate NOTCH pathway." (PMID 29262559, 2017).
cancer (continued). "At the same time, RBM5 was shown to antagonistically regulate the proliferative ability of cancer cells through alternative splicing of NUMB gene." (PMID 28061901, 2017). "Stem cell fate determination of NUMB is responsible for pluripotency and differentiation controlling, and was often suppressed in advanced carcinoma." (PMID 29262559, 2017). "miR-146a plays important roles in cancer as it directly targets NUMB, an inhibitor of Notch signaling." (PMID 27824903, 2016). "After its identification, NUMB has been extensively studied in the development of sensory organs, and subsequently in cancer research." (PMID 23841055, 2013). "While this paper was in preparation, 2 new NUMB isoforms, namely, NUMB 5 and 6 were reported and identified in the human cancer cells." (PMID 23841055, 2013). "Moreover, METTL3 also regulates the maturation of miR-146a-5p through m6A modification, further activating the NUMB endocytic adaptor protein (NUMB)/neurogenic locus notch homolog protein (NOTCH) 2 signaling pathway to promote cancer cell growth." (PMID 40747121, 2025). "Thus, the regulatory mechanisms of selective NUMB isoform expression and function in cancer cells remain to be further addressed." (PMID 37843276, 2023). "Conversely, MSI2 is a crucial regulator of cancer stem cell programs by acting on the stability and translation of target mRNAs that encode key proteins of oncogenic signaling pathways (e.g., TGFβR1/SMAD3, NUMB/Notch, PTEN/mTOR, MET, and MYC)." (PMID 37107676, 2023). "Moreover, S438 locus of NUMB peptide fragment was frequently phosphorylated in 4 cancer types and relevant to its phosphorylation sites." (PMID 37657045, 2023). "Importantly, in most cancers, the upshot supports the idea that elevated NUMB expression predicts poorer patient prognosis." (PMID 37657045, 2023). "However, it remains absent that a systematic assessment of the mechanisms underlying NUMB and its homologous protein NUMBLIKE (NUMBL) involvement in cancer." (PMID 37657045, 2023). "Notably, an additional key finding in this study, by using cBioPortal dataset, is that the genetic alternation of NUMB performs an indispensable role in multiple cancer types, especially in UCEC." (PMID 37657045, 2023). "Finally, we utilized a flow chart to show the screening procedure of NUMB/NUMBL in pan-cancer more scrupulously." (PMID 37657045, 2023). "In addition to TERT, BLCAP, and KBTBD8, we also observed low levels of damage induction in UV-irradiated melanocytes at a number of other recurrent mutations in the promoters of known or suspected cancer genes (i.e., TCF3, TOP2A, NUMB, FOSB, and OTUB2)." (PMID 37169747, 2023). "This study highlights the predictive roles of NUMB and NUMBL in pan-cancer, suggesting NUMB and NUMBL might be served as potential biomarkers for diagnosis and prognosis in various malignant tumors." (PMID 37657045, 2023). "Similarly, hypermethylation of SHISA3, KCNA3, NPY, and hypomethylation of NUMB, BST2, MAPK13 promoters, which have previously been implicated in other cancers, robustly separate normal and GBC-OSCC samples." (PMID 37245006, 2023). "In this study, we find that NUMB E12-skipping p65/p66 isoforms are mainly expressed in highly migratory cancer cell lines, whereas the E12-included p71/p72 isoforms are predominant in low migration cancer cell lines." (PMID 35457181, 2022). "We then examined how the specific knockdown of NUMB isoforms influenced cancer cell migration." (PMID 35457181, 2022). "RBM5, RBM6, and RBM10 are commonly deleted, mutated, and/or under-expressed or overexpressed genes in many cancers; however, they have different roles in in vitro colony formation assays, partially due to their antagonistic regulation of NUMB alternative splicing." (PMID 36006412, 2022).
cancer (continued). "To address whether NUMB isoforms distinctly regulate cancer cell proliferation and invasion, we separately overexpressed four isoforms in HeLa cells." (PMID 35457181, 2022). "Informatic screening of the potential miRNAs’ targets suggested that miR-146a may bind to NUMB, and NUMB decreased greatly in cancer group." (PMID 34656164, 2021). "Thus, further studies are necessary to uncover the effect of β-catenin phosphorylation and RAC1 activation in differential KRT19/β-catenin/NUMB-mediated regulation of Notch signaling crosstalk and contiguous regulation of cancer properties." (PMID 30650643, 2019). "Additionally, overexpression of NUMB can suppress cancer progression through antagonistic effects on Notch signaling." (PMID 30650643, 2019). "However, a deviation is observed in Cancer Stem Cells (CSCs) where the cell fate molecule NUMB symmetrical divided into two daughter cells." (PMID 29460395, 2018). "This difference in the role of each isoform could explain the different functions described for NUMB in different types of cancer." (PMID 30443541, 2018). "Thus, our results strongly suggest that low levels of NUMB p66 in SHH MB contribute to Shh pathway deregulation keeping cancer cells in an undifferentiated state and enhancing their cancer stemness features." (PMID 30443541, 2018). "Importantly, a second RRM domain (RRM2) of RBM10 recognizes a C-rich sequence, which explains its known interaction with the intronic 3 ́ site of NUMB exon 9 contributing to regulation of the Notch pathway in cancer." (PMID 28379442, 2017). "In this context, NUMB might be one of the molecular determinants integrating apparently distant polarized functions, including cell-fate determination of normal and cancer stem cells and EMT, which have indeed emerged as two faces of the same coin." (PMID 25767773, 2015). "Together, these novel isoforms may play a role in further understanding the NUMB function in development and cancer." (PMID 21122105, 2010). "We have presented evidence that links NUMB to RAB4A regulation for cancer cell stemness, and that loss-of-RAB4A leads to an increased expression of NUMB protein in RAB4A-high cancer cells and exogenous expression of RAB4A in RAB4A-low cells suppresses NUMB protein." (PMID 39463384, 2024). "In more detail, it has been proposed that NUMB isoforms with PRRL may be involved in the early stages of cancer development, promoting proliferation, while NUMB isoforms with PRRS may be involved in the latter stages of cancer, inducing differentiation and loss of cell polarity." (PMID 36672267, 2023). "The effects of SMAD3 and Notch1 are almost the same in cancer cell migration, as knockdown of either of the two could decrease the migration advantage seen in the overexpression of NUMB-p66, and overexpression could rescue the migration reduction seen in p65/p66 knockdown." (PMID 35457181, 2022). "However, NUMB E6 was mostly skipped in all the cancer cell lines examined." (PMID 35457181, 2022). "Thus, our data suggests that the control of NUMB alternative splicing in cancer may involve a more complex regulatory network than previously thought." (PMID 36304260, 2022). "In addition, both SETD8 and NUMB are involved in EMT-regulated diseases such as cancer." (PMID 34400910, 2021). "We suggest that Post‐translational modification of NUMB plays a crucial role in Cancer Stem Cells self‐renewal and Chemoresistance and targeting NUMB post‐translational modification could be an ideal target for therapeutics to treat chemoresistant cancer in humans." (PMID 29460395, 2018). "Several reports further indicate that NUMB may be involved in EMT in cancer." (PMID 27506933, 2016). "However, how NUMB alternative splicing is regulated in cancer had remained unclear." (PMID 24722255, 2014).